CAMK2N1 (calcium/calmodulin dependent protein kinase II inhibitor 1)
Description:
Potent and specific inhibitor of CaM-kinase II (CAMK2) (By similarity). Plays a role in the maintenance of long-term retrieval-induced memory in response to contextual fear (By similarity). Modulates blood pressure and vascular reactivity via regulation of CAMK2 activity in addition to regulation of left ventricular mass (By similarity). Mediates the NLRP3 inflammasome in cardiomyocytes via acting as an inhibitor of the MAPK14/p38 and MAPK8/JNK pathways, thereby regulating ventricular remodeling and cardiac rhythm post-myocardial infarction (By similarity). Negatively effects insulin sensitivity and promotes lipid formation in adipose tissues independent of CAMK2 signaling (By similarity).
Synonyms: CaMKIINalpha; PRO1489
Tractability: No criterion of Open Targets' tractability assessment is met for any kind of drug.
Gene: Protein-coding gene on chromosome 1 (20,482,391 to 20,486,210, reverse strand). Ensembl gene ENSG00000162545.
Subcellular location: Synapse; Cell projection, dendrite; Postsynaptic density
Subcellular location (Human Protein Atlas): Cytosol; Primary cilium
Gene Ontology:
Molecular function: calcium-dependent protein kinase inhibitor activity; protein kinase binding; protein kinase inhibitor activity
Biological process: long-term memory; positive regulation of inflammatory response
Cellular component: postsynaptic density; synapse; dendrite
Genetic constraint (gnomAD): Loss-of-function variants: 2 observed, 3.7 expected, observed/expected ratio (o/e) 0.54, 90% interval 0.22 to 1.57. That is too few expected variants to judge how well the gene tolerates losing a copy. Missense variants: 77 observed, 85.45 expected, observed/expected ratio (o/e) 0.9, 90% interval 0.75 to 1.09. Synonymous variants: 42 observed, 31.64 expected, observed/expected ratio (o/e) 1.33, 90% interval 1.04 to 1.71.
Homologues: Orthologues: chimpanzee CAMK2N1 (100% identical), dog CAMK2N1 (100% identical), guinea pig CAMK2N1 (100% identical), macaque CAMK2N1 (100% identical), pig CAMK2N1 (100% identical), mouse Camk2n1 (97% identical), rat Camk2n1 (97% identical), tropical clawed frog camk2n1 (67% identical), zebrafish camk2n1 (58% identical). Paralogues in human: CAMK2N2 (65% identical).
Diseases named in the same sentence as CAMK2N1 in open-access papers:
CAMK2N1 is named in the same sentence as 44 diseases in open-access papers, as found by Europe PMC text mining. Sharing a sentence is not in itself a finding about the gene and the disease. The quoted sentences say what the papers report.
prostate carcinoma (22 papers, 2010 to 2025). A carcinoma that arises from epithelial cells of the prostate gland. "In previous studies, increased CAMK2N1 expression has shown an association with increased prostate cancer aggressiveness." (PMID 40949143, 2025). "Docetaxel resistance is promoted in prostate cancer via CAMK2N1 downregulation, which is associated with miR-129-5p, which is in turn associated with tumor drug resistance." (PMID 38191389, 2024). "However, in gastric cancer, CAMK2N1 expression has been shown to have a carcinogenic effect and to be negatively correlated with immune infiltrate, whilst in advanced prostate cancer (PCa) CAMK2N1 overexpression was associated with aggressiveness." (PMID 40867253, 2025). "Overexpression of CAMK2N1 suppressed AKT and AR suggests that the loss of CAMK2N1 in advanced prostate cancer could be the primary cause of enhanced kinase signaling, which consequently leads to abnormal activation of AR." (PMID 25296973, 2014). "Meanwhile, miR-129-5p binds downstream DLX1, ETV1 and CAMK2N1 targets to mediate the progression of prostate cancer and affect the biological functions of cancer cells." (PMID 39003446, 2024). "The upregulated expression of the epithelial to mesenchymal transition genes CAMK2N1 and WNT5A is associated with the progression of prostate cancer." (PMID 38025757, 2023). "Camk2n1 appears to be a prognostic marker in ovarian cancer and is tumor-suppressive in prostate cancer and glioma." (PMID 37736108, 2023). "The positive feedback loop between DNMT1 and CAMK2N1 promotes the progression of prostate cancer in vivo and in vitro." (PMID 36755811, 2023). "CAMK2N1 is an endogenous inhibitor of calcium/calmodulin-dependent kinase II and has been reported as a tumor suppressor in hepatocellular carcinoma, prostate cancer, and colorectal carcinoma." (PMID 38025757, 2023). "Calcium/calmodulin-dependentprotein kinase II inhibitor I (CAMK2N1) as one of the tumor suppressor genes is significantly downregulated in prostate cancer (PCa)." (PMID 36755811, 2023). "We confirmed again that the CG sequences in the CAMK2N1 gene promoter was hypermethylated in prostate cancer cells compared to normal prostate epithelial cells." (PMID 36755811, 2023). "CAMK2N1 is commonly used as a tumor suppressor in some cancers, such as prostate cancer and hepatocellular carcinoma." (PMID 36092901, 2022). "We first analyzed CAMK2N1 protein expression in human prostate cancer specimens by performing immunohistochemical (IHC) staining." (PMID 25003983, 2014). "Our results provide a compelling rationale for targeting the functional interaction between CAMK2N1 and AR signaling in clinical development to treat castration-resistant prostate cancer." (PMID 25296973, 2014). "Reduced expression of CAMK2N1 was correlated to recurrence-free survival of prostate cancer patients with high levels of AR expression in their tumor." (PMID 25296973, 2014). "6D, we observed that overexpression of CAMK2N1 induced inhibition of growth to Casodex in castration-resistant C4–2 cells, indicating that expression of CAMK2N1 can restore Casodex sensitivity of prostate cancer cells." (PMID 25296973, 2014). "Taken together, our findings suggest that CAMK2N1 plays a tumor suppressive role and serves as a crucial determinant of the resistance of prostate cancer to endocrine therapies." (PMID 25296973, 2014). "Taken together, these data showed that CAMK2N1 regulates cell proliferation, apoptosis and tumor growth in vivo, likely through the functional interactions with these signaling molecules in prostate cancer cells." (PMID 25003983, 2014). "CAMK2N1 expression was inversely correlated with AR levels in prostate cancer, and patients with higher CAMK2N1 expression in their tumor have improved recurrence-free survival." (PMID 25296973, 2014).
prostate carcinoma (continued). "Knockdown of CAMK2N1 in prostate cancer cells alleviated Casodex inhibition of cell growth, while re-expression of CAMK2N1 in castration-resistant cells sensitized the cells to Casodex treatment." (PMID 25296973, 2014). "Taken together, our findings revealed a tumor suppressive role for CAMK2N1 and established CAMK2N1 as molecular determinant in hormone sensitivity of prostate cancer." (PMID 25003983, 2014). "Herein, we provided evidence showing in human prostate cancer tissue endogenous CAMK2N1 expression was inversely correlated with AR." (PMID 25296973, 2014). "Collectively, results from our study revealed the tumor suppressive role of CAMK2N1 in prostate cancer." (PMID 25003983, 2014). "To investigate the role of CAMK2N1 in inhibiting AR-positive prostate cancer growth in vivo, we established C4-2 cells stably transduced with lentiviral shRNAs targeting CAMK2N1." (PMID 25296973, 2014). "The mRNA level of CAMK2N1 was significantly reduced in prostate cancer tissues compared to normal prostate, which is consistent with the reduced protein expression in prostate cancer cells." (PMID 25003983, 2014). "All prostate cancer cells exhibited decreased expression of CAMK2N1, with LNCaP being closest to the control." (PMID 25003983, 2014). "In this study, we performed immunohistochemical (IHC) staining using human prostate cancer specimens and observed a significant reduction of CAMK2N1 in prostate cancer compared to normal tissue." (PMID 25003983, 2014). "We observed that overexpression of CAMK2N1 significantly impaired human prostate cancer cell proliferation and tumor growth in vivo, while depletion of CAMK2N1 promoted cell proliferation and tumor growth." (PMID 25003983, 2014). "Taken together, these results suggested a functional interaction between CAMK2N1 and AR during prostate cancer progression." (PMID 25296973, 2014). "In a prior study, we demonstrated that CAMK2N1 expression was reduced in prostate cancer, and re-introduction of CAMK2N1 significantly impaired human prostate cancer cell proliferation and tumor growth in vivo." (PMID 25296973, 2014). "We first examined the protein and mRNA levels of CAMK2N1 and observed a significant decrease in human prostate cancers comparing to normal prostate tissues." (PMID 25003983, 2014). "Next, we analyzed the abundance of CAMK2N1 mRNA in prostate cancer tissues compared to matched normal-like control from same patient (n = 10) by quantitative RT-PCR (qRT-PCR) analysis." (PMID 25003983, 2014). "In this study, we demonstrated that CAMK2N1 plays a tumor suppressive role in human prostate cancer." (PMID 25003983, 2014). "Taken together, these observations suggest that the level of CAMK2N1 is reduced in both human prostate cancer patient samples and commonly used prostate cancer cells." (PMID 25003983, 2014). "In summary, we identify a biochemical and functional link between CAMK2N1 with reduced expression in advanced prostate cancer and androgen receptor signaling in prostate cancer." (PMID 25296973, 2014). "Herein, the CAMK2N1 was shown to contribute to the human prostate cancer cell growth and survival through AR-dependent signaling." (PMID 25296973, 2014). "Similarly, high expression of miR-129-5P in prostate cancer downregulates the level of a serine/threonine-specific protein kinase (CAMK2N1), and targeting miR-129-5P sensitizes patients with prostate cancer to the chemotherapy drug docetaxel." (PMID 36936418, 2023). "In summary, this study highlights that CAMK2N1 and epigenetic pathways could be pathological biomarkers as well as the potential therapeutic targets for the effective treatment of prostate cancer." (PMID 36755811, 2023). "Additionally, miR‐129‐5p promotes proliferation, migration, and invasion and blocks apoptosis in prostate cancer cells by regulating CAMK2N1 expression." (PMID 35075115, 2022).
prostate carcinoma (continued). "Furthermore, the followed correlated gene, CAMK2N1, was also involved in immunity and acted as a tumor suppressive role in prostate cancer cells." (PMID 32957918, 2020). "To determine the functional significance of CAMK2N1 in regulating human prostate cancer growth, we first analyzed whether CAMK2N1 regulates the proliferation of human prostate cancer cells by MTT assays." (PMID 25003983, 2014). "To further determine whether CAMK2N1 inhibits oncogenic growth of prostate cancer cells, we performed colony formation assays." (PMID 25003983, 2014). "In addition, we searched the microarray data in the public domains for effects of androgens on CAMK2N1 mRNA expression in AR-positive prostate cancer cell lines, and similar observation was also made in this database." (PMID 25296973, 2014). "In addition, a moderate expression of CAMK2N1 was detected in castration sensitive LNCaP cells, while its expression was relatively low in castration-resistant prostate cancer DU145 and PC3 cells." (PMID 25003983, 2014). "In summary, we demonstrated that CAMK2N1 expression was reduced in prostate cancer." (PMID 25003983, 2014). "CAMK2N1 is significantly reduced in prostate cancer compared to benign and normal prostate tissues." (PMID 25003983, 2014). "Importantly, ectopic expression of CAMK2N1 in castration-resistant prostate cancer cells sensitized cells to response to anti-androgen treatment." (PMID 25296973, 2014). "Decreased CAMK2N1 expression correlated with more advanced stages of prostate cancer." (PMID 25003983, 2014). "Reduced CAMK2N1 expression correlates to human prostate cancer progression and predicts poor clinical outcome, indicating that CAMK2N1 may serve as a biomarker." (PMID 25003983, 2014). "Re-expression of CAMK2N1 in prostate cancer may provide clinical benefits to patients; however, further studies are warranted to determine the molecular mechanisms link between CAMK2N1 and androgen receptor signaling in prostate cancer." (PMID 25003983, 2014). "Re-expression of CAMK2N1 in prostate cancer cells reduced cellular proliferation, arrested cells in G0/G1 phases, and induced apoptotic cell death accompanied by down-regulation of IGF-1, ErbB2, and VEGF downstream kinases PI3K/AKT, as well as the MEK/ERK-mediated signaling pathways." (PMID 25003983, 2014). "Our analyses suggest that CAMK2N1 plays a tumor suppressive role in prostate cancer cells." (PMID 25003983, 2014). "Currently, it is still unknown whether CAMK2N1 plays any role in prostate cancer development." (PMID 25003983, 2014). "Furthermore, loss of CAMK2N1 expression contributes to prostate cancer growth and survival independent of androgen signaling and re-introduction of CAMK2N1 sensitizes castration-resistant prostate cancer cells to anti-androgen therapy." (PMID 25296973, 2014). "Accordingly, CAMK2N1 was not only described as tumor suppressor in EOC by our group but in multiple myeloma, oral squamous cell carcinoma, prostate cancer and thyroid cancer throughout the last years." (PMID 33482905, 2021). "One was CAMK2N1, which is an inhibitor of CAMK2 and appears to be a tumor suppressor in prostate cancer." (PMID 30555629, 2018). "However, it is still unknown whether CAMK2N1 plays a role in prostate cancer development." (PMID 25003983, 2014). "It has been reported that CAMK2N1 expression is downregulated after androgen receptor (AR) activation in human prostate cancer cell lines following an auto-regulatory negative feedback loop." (PMID 33441551, 2021). "In prostate cancer cells, CAMK2N1 and AR signaling form an auto-regulatory negative feedback loop, where CAMK2N1 is down regulated by AR activation in response to androgen, while CAMK2N1 inhibits AR expression and activity through the CAMKII and AKT pathway." (PMID 25296973, 2014). "In this study, we observed CAMK2N1 and AR signaling form an auto-regulatory negative feedback loop in human prostate cancer cells." (PMID 25296973, 2014).
ovarian carcinoma (7 papers, 2016 to 2024). A malignant neoplasm originating from the surface ovarian epithelium. "CAMK2N1 is generally considered as a tumor suppressor gene, which is reduced and associated with poor clinical outcomes in hepatocellular carcinoma, medullary thyroid cancer, cervical cancer, or ovarian cancer." (PMID 36755811, 2023). "Some of the reported hypermethylated genes in ovarian cancer are BRCA1, RASSF1A, TGFBI, DOK1, RUNX3, and CAMK2N1." (PMID 38627856, 2024). "The high expression of CAMK2N1 and MMP9, on the other hand, has already been described in xenopatients of ovarian cancer treated with cisplatin." (PMID 33922695, 2021). "We found three kinases (CAMK2N1, GRK2, and MAP3K9) to be KGDs in OCC models, compared to other ovarian cancer histologies such as serous ovarian cancer." (PMID 26947069, 2016).
oral squamous cell carcinoma (5 papers, 2020 to 2023). "In addition, miR-182-5p also promotes the growth of oral squamous cell carcinoma via reducing CAMK2N1 quantification." (PMID 35677888, 2022).
colon cancer (3 papers, 2014 to 2020). "The CAMK2N1 gene is a calcium/calmodulin-dependent protein kinase II inhibitor 1, and its expression is negatively correlated with the progression of human colon cancer." (PMID 25789025, 2015). "In addition, CAMK2N1-mediated inhibition of CaMKII activity regulates the cell-cycle progression in colon cancer cells through de-activation of MEK/ERK kinase activity and p27 protein accumulation." (PMID 25003983, 2014). "Furthermore, CAMK2N1-mediated inhibition of CAMKII activity caused deactivation of MEK/ERK kinase activity and accumulation of p27 protein, which primarily regulates the cell cycle progression of colon cancer cells, suggesting a role of CAMK2N1 in tumorigenesis." (PMID 25003983, 2014).
colorectal carcinoma (3 papers, 2021 to 2024). A malignant epithelial neoplasm that arises from the colon or rectum and invades through the muscularis mucosa into the submucosa. "CAMK2N1 inhibited HCC and colorectal carcinoma, and modulated obesity by affecting many metabolic syndrome features." (PMID 38836117, 2024).
gastric cancer (3 papers, 2020 to 2025). A primary or metastatic malignant neoplasm involving the stomach. "To confirm the reliability of the analysis results, we validated the expression of CAMK2N1 and ncRNAs in the human gastric cancer cell lines." (PMID 36092901, 2022). "There revealed significantly over-expression of CAMK2N1 in four gastric cancer cell lines (MGC-803, BGC-823, HGC-27, and MKN-45) as compared to the normal gastric mucosal cell line GES-1." (PMID 36092901, 2022). "We found that SNHG10 and CAMK2N1 were highly expressed in gastric cancer lines, and the miR-378a-3p was lowly expressed in BGC-823, HGC-27, and MKN-45." (PMID 36092901, 2022). "Correlation analysis between CAMK2N1 and biomarkers of immune cells in gastric cancer determined using the GEPIA database." (PMID 36092901, 2022). "To further validate the role of CAMK2N1, SNHG10, and hsa-miR-378a-3p in GC, we assessed the expression of mRNA and protein in gastric cancer cell lines." (PMID 36092901, 2022).
medullary thyroid cancer (3 papers, 2020 to 2023). "Although the mRNA expression of CaMKII’s endogenous inhibitor CAMK2N1 inversely correlates with the severity of medullary thyroid carcinoma, both CAMK2N1 (HR=2.1) and CAMK2A (HR=1.6) were overexpressed in the TCGA HNSCC patientswith worse outcomes." (PMID 34442426, 2021).
cervical cancer (2 papers, 2015 to 2023). A primary or metastatic malignant neoplasm involving the cervix. "Two other genes, PPP1R3C and CAMK2N1, were downregulated by hypermethylation in cervical cancer." (PMID 25789025, 2015). "Based on these data, CAMK2N1 may play important roles in cervical cancer progression through epigenetic regulation." (PMID 25789025, 2015). "From these results, the expression of the CAMK2N1, ALDH1A3 and PPP1R3C genes are were shown to be suppressed in cervical cancers by DNA methylation." (PMID 25789025, 2015).
diabetes (2 papers, 2019 to 2022). "In human visceral fat, CAMK2N1 expression correlated with adiposity and genomic variants that increase CAMK2N1 expression associated with increased risk of coronary artery disease and type 2 diabetes mellitus." (PMID 31327268, 2019). "In humans, visceral fat CAMK2N1 expression correlated with adiposity, and SNPs that regulate CAMK2N1 expression are associated with coronary artery disease and type 2 diabetes mellitus." (PMID 31327268, 2019). "Camk2n1 resides in genomic loci for blood pressure, left ventricle mass, and type 2 diabetes mellitus, and in the spontaneously hypertensive rat model of metabolic syndrome, Camk2n1 expression is cis-regulated in left ventricle and fat and positively correlates with adiposity." (PMID 31327268, 2019).
invasive breast carcinoma (2 papers, 2022 to 2023). A carcinoma that infiltrates the breast parenchyma. "We identify early processes and potential biomarkers, including CAMK2N1, MNX1, ADCY5, HOXC11 and ANKRD22, whose reduced expression is associated with the progression of DCIS to invasive breast cancer." (PMID 35697697, 2022). "Reduced expression of Camk2n1 correlates with the progression of DCIS to invasive breast cancer." (PMID 37736108, 2023).